RNU7-200P (RNA, U7 small nuclear 200 pseudogene)
Gene: Small nuclear RNA gene on chromosome 1 (20,841,241 to 20,841,302, forward strand). Ensembl gene ENSG00000251914.
Homologues: Orthologues: macaque U7 (94% identical). Paralogues in human: RNU7-97P (81% identical), RNU7-111P (77% identical), RNU7-35P (77% identical), RNU7-110P (76% identical), RNU7-120P (76% identical), RNU7-82P (76% identical), RNU7-128P (74% identical), RNU7-12P (74% identical), RNU7-138P (74% identical), RNU7-148P (74% identical), RNU7-37P (74% identical), RNU7-70P (74% identical), and 142 more.